SNORD115-43 (small nucleolar RNA, C/D box 115-43)
Synonyms: HBII-52-43
Gene: Small nucleolar RNA gene on chromosome 15 (25,249,198 to 25,249,279, forward strand). Ensembl gene ENSG00000202373.
Gene Ontology:
Biological process: RNA processing
Cellular component: nucleolus
Homologues: Orthologues: macaque SNORD115 (100% identical). Paralogues in human: SNORD115-11 (100% identical), SNORD115-29 (100% identical), SNORD115-36 (100% identical), SNORD115-12 (99% identical), SNORD115-16 (99% identical), SNORD115-22 (99% identical), SNORD115-26 (99% identical), SNORD115-39 (99% identical), SNORD115-44 (99% identical), SNORD115-6 (99% identical), SNORD115-9 (99% identical), SNORD115-10 (98% identical), and 37 more.